FLCN (folliculin)
Diseases named in the same sentence as FLCN in open-access papers (continued):
Sharing a sentence is not in itself a finding about the gene and the disease.
tumor (continued). "We further demonstrated that the mTOR inhibitor, sirolimus, suppresses the tumor's growth, suggesting that mTOR inhibitors might be effective in control of FLCN-deficient RCC, especially in BHD renal tumorigenesis." (PMID 26418749, 2015). "Taken together, these data demonstrate that loss of FLCN leads to an autophagy-dependent increase in ATP levels enabling FLCN-deficient animals/cells to resist metabolic stresses, which could constitute a tumor suppression mechanism." (PMID 24763318, 2014). "Strikingly, the majority of naturally occurring FLCN mutations predisposing to BHD were predicted to generate truncated proteins unable to bind AMPK pointing to an essential role of this interaction in the tumor suppressor function." (PMID 24763318, 2014). "Our results imply that the AMPK-dependent activation of autophagy might be essential for FLCN-deficient tumor cells to acquire an energetic advantage and drive tumorigenesis." (PMID 24763318, 2014). "Interestingly, the in-frame, tumor-associated FLCN ΔF157 mutant, was also phosphorylated during mitosis, although to a lesser degree than the FLCN WT protein." (PMID 23874397, 2013). "Thus decreased stability of mutant FLCN is likely to contribute to the loss of FLCN tumor suppressor function." (PMID 20573232, 2010). "However, it remains unclear whether synergism between EGFR/KRAS mutations and FLCN LOH accelerates tumor progression in the lung." (PMID 40630489, 2025). "These phenotype is associated with tumor development and may drive FLCN-deficient tumor growth." (PMID 33981707, 2021). "Mechanistically, Rag GTPase activity controls IRF expression to prime IFN transcription, while upon PRR stimulation, the tumor suppressor FLCN recruits p38 MAPK to lysosomes, where Rag-dependent p38 phosphorylation stabilizes Ifnb1 mRNA." (PMID 41571995, 2026). "FLCN protein loss also leads to constitutive AMPK activation, enhancing catabolism and promoting metabolic adaptations that support tumor survival and growth." (PMID 40277780, 2025). "FLCN is the causative gene of BHD and functions as a tumour suppressor that regulates cell growth, energy/nutrient homeostasis, metabolism and autophagy." (PMID 40426219, 2025). "Next-generation sequencing was performed by Caris® Life Sciences on the tumor from the thyroid, which showed a pathogenic p.M394fs mutation (VAF 82%) in the FLCN gene, indicative of biallelic inactivation (double hit) and supportive of a neoplastic process." (PMID 40277780, 2025). "Together, these cases support a potential role for FLCN as a rare primary driver in a subset of oncocytic thyroid tumors, as seen in FLCN-related tumors of the kidney and parathyroid gland." (PMID 40277780, 2025). "Altogether, our study unveils a novel role for FLCN in liver homeostasis and as a tumor suppressor in liver carcinogenesis." (PMID 40189703, 2025). "FLCN, as a tumor suppressor, is usually involved in the mTORC1 cell signaling pathway together with FNIP." (PMID 38267514, 2024). "The high protein levels of CCND1 and RB1 hyperphosphorylation in long-term FLCN knockdown HK2 tumor spheroids likely contributes to their observed tumorigenicity." (PMID 38978568, 2024). "Alterations in FLCN within renal distal tubular cells promote tumorigenesis and the development of various histological tumor phenotypes." (PMID 38963008, 2024). "Western blot analysis of pT389‐S6K and immunohistochemistry of p‐S6 demonstrated that knock in of FLCN‐SD led to mTORC1 activation in tumors, and immunohistochemistry of Ki67 showed that FLCN‐SD regulated tumor cell proliferation in an mTORC1‐dependent manner." (PMID 37083230, 2023). "Functionally, phosphorylated FLCN promotes cell viability and induces autophagy, and also regulates in vivo tumor growth in an mTORC1‐dependent manner." (PMID 37083230, 2023).
tumor (continued). "Of note, FLCN deletion in DCs rendered mice unresponsive to the beneficial anti-tumour effect of glutamine supplementation, indicating a requirement for FLCN expression in DCs in mediating this therapeutic effect." (PMID 37407815, 2023). "In renal tumors, loss of FLCN-FNIP1/2 induces a non-classical interferon response, and FNIP1 and FNIP2 are crucial for FLCN’s tumor suppressor function." (PMID 37341987, 2023). "To further confirm the relevance of modulating EGR1 to reduce TFEB-driven oncogenic properties, we developed 3D cultures from HeLa-FLCN KO cells to mimic the tumor microenvironment better." (PMID 36888606, 2023). "Loss of FLCN in DCs selectively impairs cDC1 function in vivo in a TFEB-dependent manner and phenocopies SLC38A2 deficiency by eliminating the anti-tumour therapeutic effect of glutamine supplementation." (PMID 37407815, 2023). "Together, these results indicate that FLCN is essential for cDC1s to prime anti-tumour CD8+ T cell effector responses." (PMID 37407815, 2023). "Subcutaneous tumorigenic data showed that FLCN‐SA inhibited tumor growth and tumor volume, and the level of pT389‐S6K indicated that the inhibitory effect of FLCN‐SA on tumor growth was achieved mainly through inhibition of the mTORC1 pathway." (PMID 37083230, 2023). "In conclusion, these data suggest that phosphorylation of FLCN plays an important role in tumor growth through activation of mTORC1, thus illustrating the biological significance of FLCN phosphorylation in tumor growth." (PMID 37083230, 2023). "Consistent with these functional defects, the growth of MC38 or B16-OVA tumours was increased in FlcnΔDC mice, indicating a crucial role of FLCN in DCs in restricting tumour growth." (PMID 37407815, 2023). "We also examined tumor xenograft growth in FLCN-depleted, TSC2 KO cells stably expressing FLCNF118D or a combination of FLCNF118D/ FNIP2." (PMID 36357396, 2022). "Preclinical FLCN-deficient mouse models demonstrated activation of AKT-mTOR pathway, with the mTOR inhibitor rapamycin halting renal cyst and tumor growth in these animals." (PMID 36421797, 2022). "These new co-chaperones mediate the stability of critical tumor suppressors FLCN and Tsc2 as well as the various classes of Hsp90 kinase and non-kinase clients." (PMID 35883484, 2022). "It is well established that loss of FLCN induces nuclear localization of the transcription factors TFE3/TFEB and promotes a gene expression program favorable for tumor growth." (PMID 35883484, 2022). "This information and the results of immunohistochemical analysis of the renal tumors indicated features compatible with a tumor suppressor role of FLCN." (PMID 35664771, 2022). "Despite the progress reviewed here, it remains difficult to disentangle the cellular roles of FNIP1/2 in the regulation of AMPK and TFE3 from that of FLCN tumor suppressive function." (PMID 35883484, 2022). "Even though FLCN’s function is not fully understood, it has been suggested that FLCN acts as a tumour suppressor gene interacting with FNIP1 and FNIP2 proteins, thus playing a key role in mammalian target of rapamycin (mTOR) signalling pathway." (PMID 35176117, 2022). "The tumor suppressor FLCN and its binding partner FNIP2 comprise the primary GAP complex activating RagC/D and are accordingly crucial for the phosphorylation of TFEB/TFE3 by mTORC146,50." (PMID 36357396, 2022). "The recent identification of LDHA as an intracellular target of FLCN tumor suppressor activity has established a new paradigm for the study of BHD syndrome that reconciles biochemical and genetic findings in the field." (PMID 35070081, 2022). "The FLCN gene has been implicated in the pathogenesis of BHDS and its role as a tumour suppressor gene is well established." (PMID 34229741, 2021). "Reduced TGF-β signaling associated with FLCN deficiency results in low levels of the pro-apoptotic factor Bim, which protects BHD-derived cells and tumor from apoptosis." (PMID 33981707, 2021).
tumor (continued). "Strikingly, a recent study combining an scRNA-seq approach validated by experimental mouse models discovered that the protein Folliculin (FLCN), long known as a tumor suppressor protein, plays a major role in controlling venous-to-lymphatic cell transition." (PMID 34769408, 2021). "In some studies, FLCN loss leads to downregulation of genes involved in the TGF-β pathway such as TGF-β2, INHBA, SMAD3 and THBS1, which was proposed to prevent TGF-β tumor suppressor function." (PMID 33981707, 2021). "BHDS is caused by germline mutations of folliculin (FLCN), a tumor suppressor gene located on chromosome 17p11.2." (PMID 32612654, 2020). "Together this data indicates that increased FLCN deficiency and subsequent upregulation of PGC-1α enhances energy production and provides malignant tumor cells a growth advantage that fuels renal carcinogenesis." (PMID 33022986, 2020). "The immunohistochemistry results indicated that FLCN was marginally expressed in tumor tissues compared with matched para-cancerous tissues, but HIF2α was reversed." (PMID 32850947, 2020). "BHD is caused by germline mutation in the folliculin (FLCN) gene on chromosome 17p11.2, a tumor suppressor gene known to be involved in the signaling of mammalian target of rapamycin (mTOR)." (PMID 32631372, 2020). "Here, the authors describe that Folliculin, a tumor suppressor, prevents the fusion of these vessels during development by limiting the plasticity of venous and lymphatic endothelial cells." (PMID 33298956, 2020). "We identify the tumor suppressor, Folliculin(FLCN) as a critical gene required for the exit from human pluripotency." (PMID 30733432, 2019). "Consistent with a tumor suppressor function of FLCN, tumor growth of UOK-257-2 cells, which express FLCN, was significantly suppressed when compared to that of FLCN-null UOK-257 cells." (PMID 28039480, 2017). "The FTC-133 (FLCN−/−) cells were chosen because they reproducibly produce xenograft tumours with a short latency (3–5 weeks)." (PMID 28656962, 2017). "Our work highlights a mechanism explaining, at least in part, the tumour suppressor function of FLCN." (PMID 28656962, 2017). "Folliculin (FLCN), a tumor suppressor, was originally identified from patients with Birt–Hogg–Dubé syndrome." (PMID 29018350, 2017). "Folliculin is a known tumour suppressor but the molecular mechanisms behind this function are unclear." (PMID 28656962, 2017). "The gene responsible for BHD syndrome, the folliculin (FLCN) gene on chromosome 17p11.2, is a tumor suppressor gene that was first reported in 2002 and is known to be involved in the signaling of mammalian target of rapamycin (mTOR)." (PMID 28558743, 2017). "Our findings enrich the complicated network of EGFR signaling and uncover a molecular mechanism of FLCN in tumor suppression." (PMID 29018350, 2017). "The tumor suppressor FLCN was surprisingly identified as a positive regulator of TORC1 signaling by amino acids." (PMID 27462445, 2016). "Here we show that the tumour suppressor FLCN is an Hsp90 client protein and its binding partners FNIP1/FNIP2 function as co-chaperones." (PMID 27353360, 2016). "Previous work has shown that FNIP1 and FNIP2 are critical components of the FLCN complex and are essential for its tumour suppressive function." (PMID 27353360, 2016). "Since the identification of FLCN as a tumour suppressor whose disruption is responsible for BHD syndrome, considerable effort has been focused on understanding the underlying molecular mechanisms that lead to disease." (PMID 27113757, 2016). "FLCN (folliculin), a tumor suppressor, was originally identified from patients with Birt–Hogg–Dubé (BHD) disease." (PMID 26418749, 2015). "The fact that FLCN negatively regulates AMPK strongly implicates that it exerts physiological functions other than being a tumor suppressor." (PMID 24763318, 2014).
tumor (continued). "Because we demonstrated that both LC3B and LC3C exercise important and opposite effects on growth of ccRCC tumors, we propose that the contribution of FLCN to the tumor-suppressing activity of VHL results, at least partially, from its effects on autophagy." (PMID 23922894, 2013). "We show that FLCN contributes to VHL-mediated suppression of tumor growth by affecting LC3B and LC3C autophagic pathways." (PMID 23922894, 2013). "FLCN function has been tested in classic tumor suppressor assays, such as soft agar colony formation and tumor growth in mouse xenograft assays." (PMID 23874397, 2013). "The purpose of this work was to determine if FLCN contributes to the tumor suppressing activity of VHL." (PMID 23922894, 2013). "The ability of FLCN to alter cell cycle progression in both human and mouse cells further suggests that the tumor suppressor activity of FLCN is, at least in part, mediated by its ability to affect cell cycle progression." (PMID 23874397, 2013). "Knockdown of FLCN results in increased formation of tumors by RCC cells with wild-type VHL in orthotopic xenografts in nude mice, an indication that FLCN plays a role in the tumor-suppressing activity of VHL." (PMID 23922894, 2013). "Here we reported that VHL regulates expression of FLCN and that, in turn, FLCN participates in the tumor suppressing activity of VHL." (PMID 23922894, 2013). "Since several tumor suppressor genes affect the cell cycle, we sought to investigate the potential role of FLCN on cell cycle progression." (PMID 23874397, 2013). "The nature of the direct molecular mechanism by which VHL induces FLCN renal tumor suppressors remains to be determined, but is likely to involve multiple mechanisms." (PMID 23922894, 2013). "BHD is one of the least studied monogenic tumor suppressor gene disorders, with fewer than 12 publications on the functions of FLCN." (PMID 23139756, 2012). "Genomic DNA was isolated from the tumors or tumor cell patches and PCR was performed using a primer pair specific to exon 10 and exon 11 that amplifies 664 bp of the endogenous FLCN gene or 99 bp of the FLCN transgene." (PMID 20573232, 2010). "Specifically, we found that the PGC gene set and other OXPHOS gene sets were highly negatively correlated with FLCN expression across these tumor types." (PMID 21162720, 2010). "In the current study, in order to investigate the tumor suppressor function of FLCN we have introduced wild-type FLCN into UOK257 cells and compared their growth in vitro and in vivo." (PMID 20573232, 2010). "Here for the first time we have confirmed the tumor suppressor function of FLCN in vivo and identified new potential FLCN downstream targets in the TGF-β signaling pathway." (PMID 20573232, 2010). "When these cells were injected into nude mice, tumor development was inversely dependent upon the level of wild-type FLCN expression." (PMID 20573232, 2010). "Germline mutations in BHD,plus somatic mutations and loss of heterozygosity in tumor tissue, suggest that lossof function of the folliculin protein is the basis of tumor formation inBHD syndrome." (PMID 19009041, 2008). "This case suggests FLCN loss may drive oncocytic tumorigenesis, consistent with other FLCN-driven neoplasms." (PMID 40277780, 2025). "Therefore, we explored the long-term consequences of FLCN loss through transcriptomic and proteomic analysis to better characterize FLCN as a tumor suppressor, and in doing so uncovered links to DNA-PK and cell cycle control." (PMID 38978568, 2024). "This study aimed to identify disease‐causing variants within a Chinese family affected by Birt–Hogg–Dubé syndrome (BHDS), which arises from an autosomal dominant inheritance pattern attributed to variants in the folliculin (FLCN) gene, recognized as a tumor suppressor gene." (PMID 38963008, 2024).
tumor (continued). "APC (p = 1.7e-20), BCL9 (p = 0.0006), CREBBP (p = 8.5e−5), FLCN (p = 1.39e−7), NSD2 (p = 0.002), and EP300 (p = 1.42e−6) all had significantly higher mutation rates in MSLN low expressing tumor samples compared to MSLN high expressing tumor samples." (PMID 39174744, 2024). "In sum, FLCN is selectively required for glutamine to promote the function of cDC1s but not cDC2s, concomitant with its critical importance in vivo in mediating glutamine-dependent suppression of tumour growth." (PMID 37407815, 2023). "The tumour suppressor FLCN is the GTPase activating protein (GAP) for RagC26." (PMID 36697823, 2023). "Analysis of B16-ZsGreen tumour-bearing mice indicated that FLCN-deficient cDC2s but not cDC1s exhibited migratory defects to the tumour dLNs without alterations of antigen uptake by DCs." (PMID 37407815, 2023). "To further elucidate the differences in response to kinase inhibitors between FLCNPOS and FLCNNEG RPTEC and UOK257 cells, we performed comprehensive phosphoproteomic profiling of the UOK257 (FLCNNEG) and the isogenic FLCN reconstituted tumor cell line UOK257-2 (FLCNPOS)." (PMID 35863698, 2022). "Given our evolving understanding of the molecular mechanisms through which loss of FLCN induces tumor formation, there is at yet no reliable systemic agent for the management of the clinical phenotypes of this hereditary syndrome." (PMID 36421797, 2022). "As FNIP1/2 and Tsc1 scaffold the tumor suppressors FLCN and Tsc2 to Hsp90, it follows that these co-chaperones may participate in the chaperoning of additional Hsp90-dependent tumor suppressor clients." (PMID 35883484, 2022). "Furthermore, our validation results suggested that the loss of four mTOR-related genes (PTEN, FLCN, RRAGC, and RPS6KA1) was associated with enhanced long-term proliferation and target tumor cell killing." (PMID 35990699, 2022). "Studies showed that the Rag GTPases (RRAGD) could regulate the mTORC1 signaling pathway by regulating the translocation of mTORC1 to the site of activation (lysosomal surface) and result in suppression of the folliculin tumor." (PMID 36500178, 2022). "As FNIP1/2 and Tsc1, respectively, have established roles as guardians of these tumor suppressors, it follows that there may be a role for molecular chaperones in mediating FLCN and Tsc2 stability." (PMID 35883484, 2022). "Importantly, EGFR, MET, EPHA2, MAPK1, MAPK3, and RPS6 kinase pathways were strongly dependent on FLCN in RPTEC and also strongly respond to FLCN reconstitution in this BHD tumor cell line, as highlighted in the UOK257 INKA rankings in orange." (PMID 35863698, 2022). "FLCN and Tsc2 are additions to the growing list of tumor suppressors that interact with Hsp90." (PMID 35883484, 2022). "Interestingly, loss of FEM1B led to decreased lactate production, perhaps as a byproduct of FNIP1-dependent stabilization of FLCN and its recently described tumor suppressive effect on lactate dehydrogenase A." (PMID 35883484, 2022). "The folliculin (FLCN) gene is considered to be a tumor suppressor." (PMID 33240319, 2020). "In summary, by silencing FLCN, HIF2α might move into the nucleus and activate downstream-related tumor signaling pathways." (PMID 32850947, 2020). "This indicates that FLCN contributes to the tumor-suppressing effect of VHL." (PMID 33643028, 2020). "Considering the close relationship between the FNIPs and FLCN it is not surprising that they have also been suggested to act as tumor suppressors, as mice deficient in FNIP1 and/or FNIP2 exhibit tumors in several different organs." (PMID 32195250, 2020). "This again proved that FLCN acted as a tumor suppressor gene, but its role might be more prone to maintain the normal physiological function of the cells." (PMID 32850947, 2020). "On the tumour level, the role of FLCN in CRCs in patients with BHD requires further exploration." (PMID 31857718, 2020). "Work done by Sok Kean Khoo and Laura S. Schmidt has confirmed a tumor suppressor role for FLCN." (PMID 32850947, 2020).